BRAF (B-Raf proto-oncogene, serine/threonine kinase)
Diseases named in the same sentence as BRAF in open-access papers (continued):
Sharing a sentence is not in itself a finding about the gene and the disease.
astrocytomas (75 papers, 2013 to 2026). "Tumors from 3 young-adult patients with IDG-mutant astrocytomas possessed a rare in-frame protein tyrosine phosphatase receptor type Z1 (PTPRZ1)-BRAF gene fusion and two class III BRAF mutations, the substitutions G464E and D594G." (PMID 41514664, 2026). "Genetic studies have revealed that approximately 10% of pediatric and adult astrocytomas exhibit activating mutations in the BRAF kinase, with the BRAFV600E mutation being the most common." (PMID 41050069, 2025). "Among circumscribed astrocytic gliomas, Pilocytic AS is characterized by mutations in KIAA1549-BRAF, BRAF, and NF1, while High-Grade Astrocytoma with Piloid Features exhibits alterations in BRAF, NF1, ATRX, and CDKN2A/B (methylome)." (PMID 38534769, 2024). "In adults with grade 3–4 astrocytoma, BRAF/MEK-targeted therapy was associated with improved overall survival compared with grade 3–4 patients who did not receive targeted therapy, suggesting targeted therapy has the ability to impact disease trajectory." (PMID 36854806, 2023). "Examples are BRAF mutations in pleomorphic xanthoastrocytoma (PXA) and papillary craniopharnygeoma (PCP) as well as TSC mutations in subependymal giant cell astrocytoma (SEGAs) that can be targeted by BRAF or mTOR inhibitors (e.g. vemurafenib or everolimus)." (PMID 35864412, 2022). "For astrocytoma, BRAF, ATM, CDKN2A, and EGFR mutations/amplifications were highly enriched in our cohort." (PMID 32373528, 2020). "The BRAF V600E mutation (7/57) was only observed in H3-wildtype astrocytomas, and was associated with a better prognosis in all histological grade II/III astrocytomas." (PMID 32228694, 2020). "It should be noted that the molecular profiles of astrocytomas in childrendiffer significantly from the adult variants and mainly contain mutations insuch genes as BRAF, H3F3A, and ATRX." (PMID 31413876, 2019). "The mutation V600E in BRAF (in children and adolescents)serves as a positive prognostic marker of grades I and II astrocytomas." (PMID 31413876, 2019). "Unlike KIAA1549-BRAF fusion transcripts which were near exclusively expressed in grade I astrocytomas, BRAF V600E mutation was detected in 22.6% of grade II-IV tumors but in none of the grade I tumors." (PMID 29152094, 2017). "A subset of high-grade pediatric astrocytomas into which our patient fits has a BRAF mutation and CDKN2A inactivation." (PMID 25563358, 2014). "This drug’s function has more recently been shown to be successful in BRAF p.V600E mutated pediatric malignant astrocytomas, while less data is currently available on its use in LGG patients, of which there are more studies on the combination of dabrafenib and trametinib." (PMID 37397394, 2023). "Likewise, the IDH-wildtype astrocytoma classified as (anaplastic) pleomorphic xanthoastrocytoma harbored a BRAF V600E mutation and was IDH1-wildtype detected by Sanger sequencing." (PMID 33941250, 2021). "Furthermore, 7/57 tested patients harbored the BRAF V600E mutation, all of whom were classified with H3-wildtype astrocytomas." (PMID 32228694, 2020). "However, itshould be noted that, in some cases, mutations in BRAF can befound in diffuse gliomas and malignant astrocytomas, in combination withmutations in other genes, such as CDKN2A or IDH." (PMID 31413876, 2019). "In inkk4a/ARF-deficient mice, the full length BRAF V600E could induce tumorigenesis but these more closely resembled high-grade astrocytomas." (PMID 25785246, 2015). "This study represents the most comprehensive analysis of the pharmacokinetics of vemurafenib in pediatric patients with recurrent/refractory BRAF V600E-mutant astrocytomas." (PMID 41050069, 2025).
astrocytomas (continued). "Recent breakthrough studies found that BRAF mutations, including KIAA1549: BRAF and BRAF V600E are responsible for astrocytoma progression." (PMID 37675821, 2023). "BRAF mutations, such as KIAA1549: BRAF and BRAF V600E have been linked to the progression of astrocytoma, according to our investigation." (PMID 37675821, 2023). "A study of 17 spinal cord astocytomas revealed that 80% of grade I astrocytomas harbored mutations in the BRAF genes, with 40% harboring BRAF-KIAA1549 translocation and the other 60% harboring a BRAF copy number gain." (PMID 34685506, 2021). "This correlates with our previous study where combination of everolimus with selumetinib was found efficacious in targeting the BT-40 (BRAF-V600E) astrocytoma cell line as well as NIH3T3 expressing KIAA1549-BRAF." (PMID 29156677, 2017). "In vitro and in vivo studies of paediatric astrocytoma cell lines expressing BRAFV600E mutation have been performed and show that target inhibition of mutated BRAF exerts an antiproliferative activity and slows tumour growth, improving survival." (PMID 25524464, 2014). "Alterations in BRAF have been previously identified in both pediatric low and high grade astrocytomas." (PMID 23592488, 2013). "A progression-free survival of 5-year are reported in a study on children with low diencephalic astrocytomas carried BRAF p.V600E (22%) versus the children without BRAF mutations (52%)." (PMID 37397394, 2023). "While MAPK/ERK activation has been seen across all astrocytoma types, including sporadic and NF1-associated astrocytomas, MAPK/ERK activation in NF1-associated astrocytomas is independent of BRAF alteration." (PMID 31906320, 2020). "In our cohort, canonical BRAF mutations were absent across astrocytoma samples and only one of four GG specimens featured the BRAFV600E mutation." (PMID 31822682, 2019). "The few available PLGG patient derived cell lines, such as BT-40 with BRAF-V600E, a modified astrocytoma cell line and Res189 with several malignant glioma mutations would not serve as representative models for studying BRAF-fusion signaling and drug sensitivity." (PMID 29156677, 2017). "Further supporting this hypothesis is the two-fold upregulation of PTPN9 expression in BRAFV600E pediatric astrocytoma compared to BRAF wildtype counterparts (p = 0.001)." (PMID 26023796, 2015). "One study suggests that BRAF fusion confers a less aggressive clinical phenotype in pediatric low-grade astrocytoma, which may explain the tendency for growth arrest." (PMID 26525348, 2015). "Some pediatric astrocytomas lacking the BRAF V600E mutation contain KRAS or other mutations in pathways that increase BRAF activity." (PMID 25563358, 2014). "Thus, for tumors that are driven by BRAF dimers, such as low-grade astrocytomas with KIAA2549:BRAF, sparing of ARAF may provide an improved therapeutic window relative to pan-RAF inhibition." (PMID 36963492, 2023). "Of note, spinal cord high-grade astrocytomas could be treated with targeted therapies; indeed, BRAF alteration status was demonstrated to be present in about 80% of low-grade spinal cord astrocytomas and these cases could be considered for a therapeutic approach with BRAF-MEK inhibitors." (PMID 32676456, 2020). "This cohort comprised 53 IDH1/2-mutant astrocytomas, 19 histone-mutant tumors, 7 with MAPK pathway alterations (BRAF, NF1), 19 GBM (13 pTERTmt) and 2 OD (1pTERTmt)." (PMID 41422096, 2025). "In sporadic circumscribed astrocytoma, KIAA1549‐BRAF is a documented hereditary change resulting in the combination of BRAF protein (f‐BRAF) and increased BRAF mobility." (PMID 37675821, 2023). "Notably, no mutations in BRAF were noted in any astrocytoma sample." (PMID 31822682, 2019). "In pediatric patients with central nervous system (CNS) neoplasms, such as ependymoma, medulloblastoma and infiltrating astrocytoma, WES detected clinically pertinent Tier 1 (BRAF V600E, NTRK alterations, and C19MC amplification) and Tier 2 variants (BRAF fusion transcripts)." (PMID 39523358, 2024).
astrocytomas (continued). "A few studies have shown a lack of BRAF fusions in ganglioglioma (GG), desmoplastic infantile GG/astrocytoma, dysembryoplastic neuroepithelial tumor, pilomyxoid astrocytoma (PMA), and pleomorphic xanthoastrocytoma (PXA)." (PMID 25785246, 2015). "In these intracranial astrocytoma models, the overall tumor size was decreased with BRAF inhibitor treatment, whereas no response was observed when administered with the wild-type BRAF control treatment." (PMID 25785246, 2015). "However, the absence of a BRAF alteration ultimately classified it as high-grade astrocytoma, not elsewhere classified (NEC)." (PMID 37998600, 2023). "Fusions may also provide prognostic indication, such as KIAA1549-BRAF in low grade astrocytomas, which have a more favorable outcome compared to non-BRAF fused tumors." (PMID 34863095, 2021). "This suggests that BRAF monotherapy alone may not be sufficient in BRAF-V600E mutant astrocytomas." (PMID 31181803, 2019). "Fusions involving the BRAF and KIAA1549 genes are found in nearly 80% of cerebellar grade I astrocytomas but only 50–55% of non-cerebellar grade I cases." (PMID 32771057, 2020).
pleomorphic xanthoastrocytoma (75 papers, 2013 to 2026). A WHO grade ll astrocytic tumor with a relatively favorable prognosis. "Previous pediatric studies reported that the incidence of BRAF V600E mutation ranged from 10% up to 20% in pHGGs with a higher incidence in pleomorphic xanthoastrocytoma and gangliogliomas." (PMID 40860828, 2025). "Of the two long-term surviving patients, one had gliomatosis cerebri, and the other had pleomorphic xanthoastrocytoma with BRAF V600E mutation." (PMID 38326438, 2024). "For example, the BRAF V600E mutation is frequently seen in GG and pleomorphic xanthoastrocytoma (PXA) but is also sometimes reported in PA and diencephalic diffuse glioma." (PMID 35018490, 2022). "Genetic anomalies in pLGG vary based on histology, with BRAF fusion seen more commonly in Pilocytic Astrocytoma (PA), while V600E mutation is more prevalent in pleomorphic xanthoastrocytoma (PXA) and ganglioglioma." (PMID 35599811, 2022). "The BRAF V600E mutation is seen in the majority of pLGGs (as seen in pleomorphic xanthoastrocytoma and gangliomas)." (PMID 33557011, 2021). "The increased likelihood of malignant behavior in pleomorphic xanthoastrocytoma and in BRAF p.V600E mutated tumors with CDKN2A deletion has led to a debate regarding the prognostic significance of BRAF p.V600E alone." (PMID 32164789, 2020). "BRAF V600E mutation has been identified in approximately 60% of pleomorphic xanthoastrocytomas (PXAs) and E-GBMs are thought to arise from the malignant transformation of PXAs59." (PMID 29654229, 2018). "Additional somatic alterations included BRAF p.V600E mutation in the pleomorphic xanthoastrocytoma and PTPN11, ATRX, and NF1 mutations in the diffuse astrocytoma." (PMID 28699883, 2017). "High frequencies of the BRAF V600E mutation have been reported in pleomorphic xanthoastrocytoma (PXA)." (PMID 24252190, 2013). "Lastly, BRAF mutations are also found in pleomorphic xanthoastrocytoma." (PMID 34638714, 2021). "Notwithstanding, the BRAF V600E mutation is more common in pleomorphic xanthoastrocytoma (42/64–66%) and in 15/23 (65%) of pleomorphic xanthoastrocytoma with anaplasia, characterizing BRAF V600E as a valuable marker for gene panel diagnostics in all CNS tumors." (PMID 32151273, 2020). "Additionally, BRAF V600E is associated with 60–80% of pleomorphic xanthoastrocytomas (PXA, WHO Grade II) across all age groups." (PMID 24716189, 2014). "BRAF V600E mutation is found in multiple types of pLGGs such as ganglioglioma, diffuse astrocytoma (DA) and Pleomorphic Xanthoastrocytoma (PXA)." (PMID 38318325, 2023). "Pleomorphic xanthoastrocytoma (PXA) are rare but have a high rate of BRAF V600E mutations (~70%) and a low rate of fusions." (PMID 31466300, 2019). "Notably, co-occurrence of BRAF V600E mutation and CDKN2A co-deletion moreover showed a significant enrichment in pleomorphic xanthoastrocytoma, a PLGG type known for an increased tendency of malignant transformation to sHGG." (PMID 39056798, 2024). "Notably, co-occurrence of BRAF V600E mutation and CDKN2A co-deletion moreover showed a significant enrichment in pleomorphic xanthoastrocytoma, a PLGG type known for an increased tendency towards malignant transformation." (PMID 39056798, 2024). "Histologic significance: Unlike PLGNTs with KIAA1549-BRAF fusions, tumors with BRAF p.V600E SNVs are histologically diverse, with this mutation occurring in up to 80% of pleomorphic xanthoastrocytoma (PXAs), 40% of PDLGGs, and 45% of GGs." (PMID 33779771, 2021). "pLGG in vitro cell line models derived from human primary tumors range from PA with a BRAF-fusion or -V600E mutation only (DKFZ-BT66, -BT308, -BT314, and -BT317) or NF1 loss (JHH-NF1-PA1), to pleomorphic xanthoastrocytoma (PXA) with BRAFV600E mutation and CDKN2A/B deletion (BT40)." (PMID 38789691, 2024).
multiple myeloma (74 papers, 2012 to 2025). "Target treatment has been successfully used in multiple myeloma, as it is the case also in patients harbouring BRAF mutations, that can be effectively treated with a combination of BRAF and MEK inhibitors." (PMID 40576686, 2025). "Trametinib, which is an MEK inhibitor, and dabrafenib, which is a BRAF inhibitor, are used to treat solid tumors, lymphomas, or multiple myeloma with BRAF V600E driver mutation." (PMID 41465489, 2025). "In this line, increased Ser synthesis is associated with bortezomib resistance in multiple myeloma and BRAF inhibitor resistance in different types of cancers." (PMID 40640948, 2025). "In this study, our goal is to assess the clinical implications of KRAS/NRAS/BRAF mutations in myeloma patients, as these mutations have potential implications for targeted therapy." (PMID 37212518, 2023). "Phase II studies have shown the efficacy of BRAF inhibition in multiple myeloma with BRAF V600E mutation." (PMID 36900299, 2023). "Mutations in the RAS‐MAPK pathway, such as KRAS, NRAS, and BRAF, are known as high‐risk factors associated with poor prognosis in patients with various cancers, but studies in myeloma have yielded mixed results." (PMID 37212518, 2023). "RAS/BRAF mutations occur in 30%–40% of myeloma cases and are associated with higher tumor burden, higher R‐ISS stage, complex karyotype, and shorter overall survival and progression‐free survival." (PMID 37212518, 2023). "We therefore systematically analyzed the clinicopathologic, cytogenetic, and molecular genetic features as well as OS in a large group of myeloma patients with KRAS/NRAS/BRAF mutations." (PMID 37212518, 2023). "RAS/BRAF mutations in myeloma offer a potential opportunity to use a targeted approach with MAPK–ERK inhibitors." (PMID 37212518, 2023). "The BRAF-V600E/K mutation, the best documented small molecule target in myeloma, was present in 2.1% of patients in our cohort, in agreement with previous reports." (PMID 38035078, 2023). "Clinical and laboratory characteristics of patients with plasma cell myeloma according to KRAS/NRAS/BRAF mutation status." (PMID 37212518, 2023). "Activating BRAF mutations have been identified in 2%–5% of myeloma patients and have therapeutic relevance." (PMID 37212518, 2023). "RAS/BRAF mutations occur in 30‐40% of myeloma cases and are associated with a higher tumor burden, higher R‐ISS stage, complex karyotype, and shorter overall survival and progression‐free survival." (PMID 37212518, 2023). "In BRAF-mutated multiple myeloma under BRAF/MEK inhibitor, DTPs also show an upregulation of OxPhos." (PMID 35681591, 2022). "One out of two solitary plasmacytoma cases was positive for BRAFV600E (BRAF:c.1799 T > A, p.(Val600Glu)) mutation and one out of four AL amyloidosis cases showed an isolated IDH1 mutation." (PMID 36138464, 2022). "The VE-BASKET study, which treated multiple BRAF V600-mutated tumors with vemurafenib monotherapy, observed a 33% response rate among the 9 multiple myeloma patients included." (PMID 35127532, 2021). "Cobimetinib in combination with ixazomib and pomalidomide is also being further investigated in the MYDRUG umbrella protocol in NRAS, KRAS, and BRAF-mutated myeloma." (PMID 35127532, 2021). "Recent studies have revealed that BRAF mutation enhances proteasome capacity and resistance to proteasome inhibitors in myeloma patients." (PMID 33467521, 2021). "The phase 2 CAPTUR study will treat a variety of tumor types, including multiple myeloma, according to targetable genetic abnormalities with BRAF V600-mutated disease receiving vemurafenib plus cobimetinib (NCT03297606)." (PMID 35127532, 2021). "The clinical experience of BRAF‐targeted therapy in myeloma patients harboring B‐RAF mutation is still limited." (PMID 35847743, 2020).